MRPL43 (mitochondrial ribosomal protein L43)
Synonyms: L43mt; MRP-L43; bMRP36a; mL43
Tractability: Small molecule: a structure with a bound ligand is known. PROTAC: ubiquitination databases record sites on it; its protein half-life has been measured.
Gene: Protein-coding gene on chromosome 10 (100,969,458 to 100,990,450, reverse strand). Ensembl gene ENSG00000055950.
Subcellular location: Mitochondrion
Subcellular location (Human Protein Atlas): Mitochondria; Nucleoplasm
Pathways (Reactome):
Metabolism of proteins: Mitochondrial ribosome-associated quality control; Mitochondrial translation elongation; Mitochondrial translation initiation; Mitochondrial translation termination
Gene Ontology:
Molecular function: protein binding; RNA binding; structural constituent of ribosome
Biological process: mitochondrial translation; translation
Cellular component: mitochondrial large ribosomal subunit; mitochondrion; mitochondrial inner membrane; mitochondrial ribosome
Genetic constraint (gnomAD): Loss-of-function variants: 13 observed, 14.65 expected, observed/expected ratio (o/e) 0.89, 90% interval 0.58 to 1.41. The upper end of that interval is the gene's LOEUF score, 1.41, which puts it in group 5 of 6, group 1 being the genes least tolerant of losing a copy. Missense variants: 211 observed, 242.32 expected, observed/expected ratio (o/e) 0.87, 90% interval 0.78 to 0.98. Synonymous variants: 116 observed, 103 expected, observed/expected ratio (o/e) 1.13, 90% interval 0.97 to 1.31.
Homologues: Orthologues: chimpanzee MRPL43 (98% identical), macaque MRPL43 (96% identical), pig MRPL43 (91% identical), dog MRPL43 (89% identical), guinea pig MRPL43 (88% identical), rat Mrpl43 (84% identical), mouse Mrpl43 (82% identical), rabbit MRPL43 (69% identical), tropical clawed frog mrpl43 (62% identical), zebrafish mrpl43 (53% identical), Drosophila melanogaster mRpL43 (40% identical), Caenorhabditis elegans mrpl-34 (31% identical).
Diseases named in the same sentence as MRPL43 in open-access papers:
MRPL43 is named in the same sentence as 3 diseases in open-access papers, as found by Europe PMC text mining. Sharing a sentence is not in itself a finding about the gene and the disease. The quoted sentences say what the papers report.
colorectal cancer (1 paper, 2025). A primary or metastatic malignant neoplasm that affects the colon or rectum. "The expression of MRPL43 is significantly increased in colorectal cancer tissues." (PMID 40371222, 2025).
cancer (1 paper, 2023). A tumor composed of atypical neoplastic, often pleomorphic cells that invade other tissues. "By using the search function of the CancerSplicingQTL database, it was found that splicing events such as ULK3_AD_31756, NDUFS5_AD_1869, and MRPL43_AD_12856 were significantly correlated with the corresponding SNPs rs12898397, rs2863095, and rs1122472 respectively in most of the analyzed cancers." (PMID 37810965, 2023).
MRPL43 also shares sentences with these, for which no sentence is quoted: sarcoidosis (1 paper).